WNT4 (Wnt family member 4)
Diseases named in the same sentence as WNT4 in open-access papers (continued):
Sharing a sentence is not in itself a finding about the gene and the disease.
tumor (continued). "WNT4 had decreased expression (logFC = −1.6), and the expression of seven mRNAs (CDK4, MAPK1, TGFB, ZEB2, AURKA, SOX4, and ADAM9) in tumor samples was not notably different from that in the group of normal tissues." (PMID 35453574, 2022). "Human papillomavirus-induced E6 protein can increase WNT4 to activate the non-canonical WNT4/PCP/JNK pathway to promote cell proliferation in vitro and tumor growth in vivo." (PMID 34642299, 2021). "It is unclear whether similar mechanisms may be maintained in ILC cells, whether ILC-derived WNT4 can signal in a paracrine mechanism with the tumor microenvironment, or whether WNT4 operates in a cell-autonomous vs nonautonomous manner to drive proliferation of tumor cells." (PMID 27650553, 2016). "In non‐tumour mice, SIRT6 over‐expression did not influence Wnt4 mRNA expression; however, in tumour‐bearing mice, gastrocnemius muscles of Tu‐Sk.T6Tg mice showed a significant downregulation of Wnt4 mRNA levels, compared with that in Tu‐CN mice." (PMID 34212132, 2021). "In addition, we identified that E6 can selectively upregulate the translation of WNT4, JIP1, and JIP2, resulting in the activation of the noncanonical WNT/PCP/JNK pathway to promote cell proliferation in vitro and tumor growth in vivo." (PMID 31637011, 2019). "Thus, the auto-regulatory negative feedback loop that controls expression of Wnt4 and EAF proteins may play an important role in both embryonic development and tumor suppression." (PMID 20161747, 2010).
cancer (50 papers, 2010 to 2025). A tumor composed of atypical neoplastic, often pleomorphic cells that invade other tissues. "Given the increased cancer risks associated with WNT4 SNPs, developing mechanistic links between WNT4 genotype, signaling, and cancer progression is also critical." (PMID 38112643, 2024). "Wnt4 is a member of the Wnt family, and previous reports have shown that abnormal Wnt4 expression is associated with carcinogenesis, and it regulates the proliferation of cancer stem cells in response to progesterone." (PMID 33060569, 2020). "Though WNT4 engages cell- and tissue-specific downstream pathways that are not well defined, converging phenotypes in reproductive tissues and associated cancers suggest that understanding WNT4 regulation and signaling can provide new insights into cancers primarily affecting women." (PMID 38112643, 2024). "Dysregulation or variants of Wnt4 gene may disturb these host networks, leading to the malignant transformation of cells and the occurrence of many cancers." (PMID 32923386, 2020). "WNT4 is higher in cancerous tissues, but decreases in the supportive tissue surrounding cancer cells as the disease advances." (PMID 39857952, 2025). "From the Cancer Hallmarks perspective, genes such as BMPR2, MICB, CLDN23, and WNT4 were linked to critical processes such as Replicative immortality, resistance to cell death, evading immune destruction, and angiogenesis." (PMID 40863222, 2025). "There were 58.40% WNT4-positive cells in the lamina propria and 6.90% in the epithelium of cancers at the Dukes A stage." (PMID 39857952, 2025). "There was also a significant decrease in WNT4-positive cells between cancers staged as Dukes A and C (p < 0.001)." (PMID 39857952, 2025). "With cancer metabolism increasingly tractable as a treatment target, there is an urgent need to better define WNT4-mediated mechanisms of metabolic reprogramming." (PMID 38112643, 2024). "Wnt4 loaded in cancer-derived exosomes is conducive to the angiogenesis of cancer via the β-catenin signalling pathway." (PMID 38341827, 2024). "Collectively, we can conclude that WYC-209 played an anti-cancer part in GC both in vitro and in vivo by down-regulating WNT4, at least partially." (PMID 38178596, 2024). "Estrogen responsiveness and Wnt4 activation are common characteristics of many cancers, even if the mechanisms downstream of Wnt4 are context-specific." (PMID 38346980, 2024). "In this study we showed that addition of exogenous testosterone reduced apoptotic signals, such as p21, while increasing cancer stem cell markers WNT4 and LGR6." (PMID 37046723, 2023). "A novelty of our approach is the comparison of WNT4 gene expression between control and EC samples, taking into account not only grade but also other cancer features." (PMID 37835474, 2023). "WNT4 also has a pro-carcinogenic role in many cancer types and is involved in immune and respiratory physiology pathways." (PMID 37159502, 2023). "As for cell–matrix interactions, CD44 appears as a possible candidate since it is expressed by neoplastic pTECs preferentially in 3D cultures as well as in aggressive TETs in vivo and—together with WNT4—is a marker of cancer stem cells." (PMID 35965500, 2022). "High expression of WNT4 plays an important role in the development and progression of these cancers by improving the cancer cell proliferation, migration, and invasion capacities." (PMID 34642299, 2021). "In the present study, loss of PTEN in FTE led to the enrichment of cancer stem cell markers such as LGR5, WNT4, ALDH1, CD44." (PMID 33828085, 2021). "WNT4, HGF and TGFB1 are associated with the molecular signaling pathways in cancer, proteoglycans in cancer, and the relaxin signaling pathway." (PMID 33959508, 2021). "The activation of Wnt4/FZD6 involves in the different diseases such as cancer, embryonic development, bone marrow mesenchymal stem cell dysfunction." (PMID 32616722, 2020).
cancer (continued). "As classic signaling molecules, EV-shuttled Wnt signaling molecules, such as Wnt 11, Wnt3a, Wnt5b, and Wnt4, have been reported to be involved in cancer progression." (PMID 33234148, 2020). "Previously, EV-mediated transfer of Wnt 11, Wnt3a, Wnt5b, and Wnt4 has been described in the progression of various cancers." (PMID 33234148, 2020). "WNT4 influences hematopoietic progenitor cell expansion and survival; however, WNT4 function in cancer development and the resulting implications for oncogenesis are poorly understood." (PMID 24274766, 2013). "WNT4 has also been observed to play a role in other cancer types, particularly breast cancer, where it may contribute to aberrant cell proliferation." (PMID 39857952, 2025). "We further examine how convergent mechanisms of WNT4 dysregulation impact cancer metabolism." (PMID 38112643, 2024). "Interestingly, WNT4 expression in these cancers is accompanied by increased levels of FZD6 and MYC, i.e., features that we detected in aggressive TETs previously." (PMID 35965500, 2022). "FOXC2, a known oncogene in several types of cancer, induces WNT4 in myoblast cell lines." (PMID 34298659, 2021). "Finally, we discuss the expression and function of WNT4 signaling in human diseases, including cancer, tissue fibrosis, wound-healing, bone metabolism, and diabetic disorders." (PMID 34642299, 2021). "In addition, recent reports suggest that the abnormality of WNT4 signaling is involved in various cancers and ovary, kidney, bone, and metabolic disorders." (PMID 34642299, 2021). "A significant number of our cancer samples had high levels of Wnt-4 expressions." (PMID 34945091, 2021). "WNT4 plays a pro-carcinogenic role in numerous cancer types." (PMID 34642299, 2021). "So, inhibition of the WNT4 pathway is a possible treatment target of cancer disease." (PMID 34642299, 2021). "Cancer cells often required mesenchymal phenotype to enhance their ability of invasion and metastasis, which is consistent with our finding that WNT4 could promote EMT in CRC cells to promote the invasion and migration ability both in vitro and in vivo." (PMID 33222684, 2020). "Likewise, several studies have described the influence of hypoxia on EVs of different cancer types: hypoxic EVs stimulate cancer angiogenesis via Wnt4, miR-135b and miR-23a, and invasion and metastasis through a processes mediated by RAB22A." (PMID 32183388, 2020). "Future studies on WNT4 regulation of autophagy may provide further mechanistic insight into novel functions of WNT4 and identify unique metabolic vulnerabilities as a treatment approach for WNT4-driven cancers including ILC." (PMID 33053661, 2020). "In early stage recurrence, the significant pathway associated genes upregulated were MMPs and genes associated with cancer cell adhesion/motility including CDC42, RAC1 while a significant upregulation of WP genes including Wnt4 and Wnt16 was noted during stage IIIc recurrence." (PMID 27902969, 2017). "Furthermore, there are several reports that over-expression of WNT4 is induced by its mutated regulator genes such as beta-catenin and GSK3B or aberrant expression of miRNAs in various cancer types." (PMID 23843947, 2013). "Importantly, target genes involved in epithelium development (RGMA, SHANK3, PAX6, PFN1, WNT4) and cancer (CBL, CYCS, FGF7, IGF1R, PTEN, PIK3CD, WNT4) address to a further role in the onset of epithelial abnormalities and oncogenesis." (PMID 23936163, 2013). "Notably, this included TGF-β (TGFB1, TGFB3), drivers of adenosine-mediated immune suppression (NT5E (CD73), ENTPD1 (CD39)), Wnt pathway ligands (WNT7A, WNT4), IL10 and drivers/markers of cancer-associated fibroblast activation (INHBA, WNT7A, TGFB1, FAP, PDGFRA, PDGFRB)." (PMID 39568014, 2024). "Furthermore, over-expression of WNT4 leads to the development of malignant tumors." (PMID 23843947, 2013).
cancer (continued). "This cancer cell subpopulation also showed statistically significant elevated expression of WNT7B, WNT7A, WNT10A and WNT4 besides the CSC markers, compared to the rest of the PDAC cells." (PMID 38678032, 2024). "We then analysed the expression of WNT ligands (WNT7B, WNT9A, WNT3A, WNT4) in RBL2-LOH cancer cell lines (HCC1500 and Cal-51) and in RBL2-wildtype cancers (MCF7 and T47D)." (PMID 38678032, 2024). "High testosterone increased the expression of WNT4 and LGR6, which have both been described as cancer stem cell (CSC) markers in both human tissues and immortalized cell lines." (PMID 37046723, 2023). "E2F1 and E2F4 chromatin immunoprecipitation sequencing (ChIP-seq) data analyses from cancer cells (E2F1 ChIP-seq, E2F4 ChIP-seq, RBL2/p13055) further indicated the binding of E2F1 and E2F4 in the proximity of WNT4 and WNT8A." (PMID 37725511, 2023). "Target gene analysis for these tsRNAs showed them to be cancer-related involving TGF-β and Wnt-signalling-pathways as well as regulating genes AKT1, MRAS, and WNT4." (PMID 35409051, 2022). "These exosomes transfers Wnt4 depending on HIF-1α which in turn activates the β-catenin signaling pathway and facilitates metastasis, contributing to cancer progression." (PMID 35496046, 2022). "Earlier we preliminarily confirmed the anti-cancer role of WYC-209 on GC cells and this function may be addressed by suppressing WNT4 expression." (PMID 38178596, 2024). "On the negative side, WNT4 is highly expressed in cancer tissues, playing a pro-carcinogenic role in many cancer types." (PMID 34642299, 2021). "All proteins (Wnt4, MMP7, CD1 and c-MYC) tested were expressed in penile tissue (141 penile tissue cores from 101 unique tissue samples of which 18 were normal/cancer adjacent and 83 were malignant samples)." (PMID 25901368, 2015). "Moreover, a negative correlation was observed between miR-497 and the WNT4 expression levels in CRC cancer tissues and paired adjacent tissues (P < 0.01)." (PMID 33222684, 2020). "Recently, tetramethylthiuram disulfide, an important pesticide extensively used in agriculture, was proved to reduce the growth performance of chickens by inhibiting the expression of Wnt4, whereas its application and efficacy in treating human malignancies have not been reported." (PMID 32923386, 2020). "However, a WNT4-driven autocrine loop has not been described so far in another cancer type to our knowledge and may be one more unique molecular peculiarity of TETs." (PMID 35965500, 2022).
infection (6 papers, 2007 to 2024). The state of being infected such as from the introduction of a foreign agent such as serum, vaccine, antigenic substance or organism. "For instance, infection of chick limbs using a retrovirus carrying Wnt5a or Wnt4 presented distinct effects, with Wnt5a delaying chondrocyte differentiation, whereas Wnt4 accelerated it." (PMID 17505543, 2007). "The authors proposed that this might be the result of a low infection efficiency or low dose of Wnt4 protein." (PMID 19878558, 2009). "Long-term infection of DENV-2 downregulated the expression of hair growth regulatory factors, such as Rip1, Wnt1, and Wnt4." (PMID 32121148, 2020). "qRT-PCR in WS1 showed that Rip1, Wnt1, Wnt4, and cMyc expressions were inducted by DENV-2 (MOI 1, 5, and 10) after one and/or two days of infection, but decreased at day 33 post-infection, particularly in the MOI 5 and 10 infected WS1 cells." (PMID 32121148, 2020). "In HFDPCs, the increased levels of Rip1, Wnt1, and Wnt4 were only detected at day 1 after DENV-2 infection, but decreased at days 2 and 33 in comparison to the mock infection." (PMID 32121148, 2020). "However, an in vitro micromass culture assay has shown that infection by a retroviral-delivered Wnt4 did not decrease the rate of cell proliferation." (PMID 17505543, 2007).
kidney diseases (6 papers, 2020 to 2023). "WNT4 mRNA and protein expression was absent in normal adult kidneys, until renal injury or onset of kidney diseases caused the activation of WNT4 expression." (PMID 32365994, 2020). "A study on WNT4 expression in human kidney diseases demonstrated that changes in WNT4 mRNA levels correlated with some clinical parameters depending on the specific disease." (PMID 35886848, 2022). "In many cases, carcinogenesis uses different developmental processes, so it was logical to investigate the expression of Wnt-4, which has already been shown to play an important role in various renal diseases." (PMID 34945091, 2021). "In this study, we investigated the immunohistochemical expression of one member of the Wnt family, Wnt-4, which has been attributed the most important role not only in kidney development, but also in different kidney diseases." (PMID 34945091, 2021). "The absence of Wnt4 mRNA and protein has been observed in fully functional kidneys just before renal damage or inception of kidney diseases." (PMID 37107656, 2023). "Wnt-4 expression in ccRCC as well as in different kidney diseases is complex and not unambiguous." (PMID 34945091, 2021).
gynecologic tumor (1 paper, 2024). "These gynecologic tumor data parallel our observations in ILC and support that WNT4 underpins metabolic remodeling." (PMID 38112643, 2024).
heart disease (1 paper, 2022). "In all, our findings demonstrate an antifibrotic and proendothelial roles of Wnt4 in cardiac repair which not only provide new insight into the mechanism for cardiac repair, but also provide a potential gene to precisely regulate MEndoT for treatment of heart disease." (PMID 35673578, 2022).
metabolic disease (1 paper, 2016). A congenital disorder (due to inherited enzyme abnormality) or acquired (due to failure of a metabolically important organ) disorder resulting from an abnormal metabolic process. "Our findings showed that GLP-1 promoted adipogenesis through the modulation of the Wnt4/β-catenin signaling pathway, suggesting that the GLP-1-Wntβ-catenin system might be a new target for the treatment of metabolic disease." (PMID 27504979, 2016).
myopathy (1 paper, 2023). A disease of the muscle in which the muscle fibers do not function properly. "Furthermore, RNA-seq data showed alterations in several genes involved in Wnt signaling, such as APC, DACT1, DKK2, DVL2, and WNT4, emphasizing an important role for Wnt signaling in WB myopathy." (PMID 38130476, 2023).
WNT4 also shares sentences with these, for which no sentence is quoted: cardiovascular diseases (3 papers); Primary amenorrhea (3); Uterine leiomyoma (3); brain tumors (2); chronic kidney disease (2); colorectal (2); diabetic nephropathy (2); Dupuytren disease (2); endothelial dysfunction (2); idiopathic pulmonary fibrosis (2); ischemia (2); kidney failure (2); liver fibrosis (2); osteoarthritis (2); pancreatic cancer (2); rectal cancer (2); Stroke (2); thymic carcinoma (2); Ureteral obstruction (2); adenocarcinoma (1); adenomyosis (1); aortic stenosis (1); apical periodontitis (1); asthma (1); autoimmune disease (1); Azoospermia (1); benign tumors (1); breast adenocarcinoma (1); cervical (1); colorectal adenocarcinoma (1).
A further 50 diseases each share a sentence with WNT4 in 1 paper.